TYR (tyrosinase)
Diseases named in the same sentence as TYR in open-access papers (continued):
Sharing a sentence is not in itself a finding about the gene and the disease.
melanoma (continued). "Some data attribute resveratrol depigmenting affect to its ability to reduce Mitf and tyrosinase promoter activities in B16 mouse melanoma cells." (PMID 19865532, 2009). "Accordingly, it has been demonstrated that substances that act as selective inhibitors of V-ATPase are able to determine the re-activation of tyrosinase and melanogenesis and melanotic reversion of amelanotic melanomas." (PMID 19133143, 2009). "The compound contains two mechanisms to reduce melanogenesis in melanoma cells, including inhibiting tyrosinase activity and reducing the expression of tyrosinase." (PMID 19582213, 2009). "A study completed investigating the biochemical effect of α-TF in human melanoma cells suggests the whitening effect is due to tyrosinase inhibition at the post-transcriptional level, possibly by an unidentified secondary molecule." (PMID 19865532, 2009). "In this study, the compound was evaluated for in vitro cellular tyrosinase and melanogenesis inhibitory activities in mouse B16 melanoma cells and for in vivo skin-whitening activity in human volunteers." (PMID 20057943, 2009). "The expression of the HPV16-E5 oncoproteins was induced in two Tyrosinase-positive amelanotic melanomas (the cell lines FRM and M14) by a retroviral expression construct." (PMID 19133143, 2009). "Tyrosinase is an enzyme involved in the initial stages of melanin biosynthesis in melanocytic and melanoma cells and its hyperexpression has been proposed as a biochemical marker of melanoma." (PMID 18445301, 2008). "Small molecule inhibition of a family of gene products in this class was sufficient to impair chronic tyrosinase expression in pigmented melanoma cells and UV-induced tyrosinase expression in primary melanocytes." (PMID 19057677, 2008). "Studies in malignant melanoma patients showed that detection of mRNA of the enzyme tyrosinase by RT–PCR reaction in sentinel lymph nodes (SLN) correlates with disease recurrence and survival." (PMID 16495929, 2006). "The discriminatory immunostaining pattern associated with the 'MCW Melanoma Cocktail' (mixture of Melan- A, MART- 1, and tyrosinase) facilitated the feasibility of intraoperative evaluation of imprint smears of SLNs for melanoma metastases." (PMID 15500702, 2004). "In this study, the RT–PCR technique was used to detect the presence of tyrosinase mRNA in the peripheral blood of a cohort of 110 stage III disease-free melanoma patients, both at diagnosis and during follow-up, until disease progression." (PMID 14562017, 2003). "Several studies have suggested a potential clinical use of the RT–PCR analysis of tyrosinase mRNA to detect circulating neoplastic cells in the peripheral blood of melanoma patients." (PMID 14562017, 2003). "For detecting tumour cells in melanoma patients reverse transcription-polymerase chain reaction (RT–PCR) has been used to identify tyrosinase, a key enzyme in melanin biosynthesis, in the circulation of patients with disseminated disease." (PMID 12107840, 2002). "The tyrosinase gene is actively expressed only in melanocytes and melanoma cells and as melanocytes cannot be detected in the circulation, the detection of tyrosinase RNA indicates the presence of melanoma cells." (PMID 12107840, 2002). "The Melanoma Cooperative Group performed RT–PCR using tyrosinase, p 97, MUC 18, and MelanA/MART1 as gene markers in 235 patients with either localised or metastatic melanoma." (PMID 12107840, 2002). "In another study where blood samples from 276 melanoma patients were tested for tyrosinase and MART-1 at multiple sequential time points for at least 2 years after surgery, a low incidence of RT–PCR positivity was observed even up to 2 years after surgery." (PMID 12107840, 2002). "Four hundred and eighteen blood samples from 60 melanoma patients were tested for tyrosinase mRNA in blood by RT–PCR." (PMID 12107840, 2002).
melanoma (continued). "The RT–PCR positivity by tyrosinase mRNA in blood during follow-up of patients with melanoma significantly correlated with shorter disease-free survival (P: 0.029)." (PMID 12107840, 2002). "The specificity and sensitivity of the nested reverse transcriptase polymerase chain reaction (RT-PCR) on tyrosinase was studied, for the detection of micrometastases of malignant melanoma." (PMID 10901368, 2000). "The clinical value of the reverse transcription polymerase chain reaction (RT-PCR) assay for tyrosinase in peripheral blood of melanoma patients is still under debate." (PMID 10638977, 2000). "In recent years, large discrepancies were described in the success rate of the tyrosinase reverse transcription polymerase chain reaction (RT-PCR) for detecting melanoma cells in the peripheral blood of melanoma patients." (PMID 10360670, 1999). "This compound, bisMSH-DTPA, was equipotent with MSH in an in vitro tyrosinase assay with Cloudman S91 melanoma cells." (PMID 2257220, 1990). "In this study, we present a strategy for in situ polymerization of a porphyrin derivative within melanoma cells triggered by tyrosinase, and subsequent self-assembly of the polymers into microstructures limiting porphyrin efflux, to achieve "precision medicine" for melanoma." (PMID 42003804, 2026). "This study aimed to evaluate the effects of maculosin, a cyclic dipeptide composed of tyrosine and proline, on melanin production and tyrosinase activity using the B16F10 melanoma cell model, while elucidating its mechanism of action through molecular docking and molecular dynamics (MD) simulations." (PMID 40005169, 2025). "Quercetin, as a main component in pomegranate flower ethanol extract, decreases the intracellular tyrosinase activity against melanogenesis by mouse melanoma cells and improves the antioxidant capacity by regulating MAPK, NRFB, AMPK, and other signaling pathways induced by ROS." (PMID 40232012, 2025). "To validate whether our iCRISPRa/i systems could induce phenotypic changes by controlling endogenous gene expression, we set to regulate tyrosinase (Tyr) gene transcription in the B16 melanoma cells." (PMID 40549156, 2025). "siRNA targeting iP beta subunits (LMP2, LMP7, and MECL1) is used to modify the expression of iP-mediated antigen processed by dendritic cells, in combination with RNAs encoding melanoma TAAs (MART-1, tyrosinase, gp100, and MAGE-3), to enhance antigen-specific T cell responses." (PMID 40943628, 2025). "Indeed, studies have shown that tyrosinase inhibition can lead to reduced melanin synthesis, reduced tumor growth and metastasis in melanoma models." (PMID 40332760, 2025). "We have validated that this TYR-catalyzed prodrug activation approach could effectively retain the intracellular drug concentration to resensitize the drug-resistant melanoma cells to chemotherapeutics both in vitro and in vivo." (PMID 40651969, 2025). "In male mouse models, we show that this TYR-catalyzed therapeutics could efficiently alleviate skin hyperpigmentation within 48 h as well as resensitize the drug-resistant melanoma cells to chemotherapeutics to control tumor growth." (PMID 40651969, 2025). "Importantly, the activator of tyrosinase expression, the microphthalmia-associated transcription factor (MITF), plays oncogenic roles in melanoma." (PMID 41002986, 2025). "Genetic analyses further support shared susceptibility, as pigmentation-related variants near ASIP (encoding agouti signaling protein), TYR (encoding tyrosinase), and TYRP1 (encoding tyrosinase-related protein 1) were associated with both melanoma and BCC in European populations." (PMID 41374951, 2025).
melanoma (continued). "Interestingly, AZA has been found to competitively suppress the +action of the tyrosinase enzyme in cultured human keratinocytes, melanocytes, melanoma cells, murine melanoma cells, and in purified enzymes from Escherichia coli, rat liver, and human melanoma." (PMID 40362596, 2025). "Tyrosinase is an increasingly promising target for melanoma treatment." (PMID 40332760, 2025). "Targeting tyrosinase may also be an approach to treating melanoma, a malignant tumor of melanocytes characterized by excessive melanin production." (PMID 40332760, 2025). "This specificity could enhance treatment efficacy and minimize side effects, establishing tyrosinase as a valuable target in the fight against melanoma." (PMID 40332760, 2025). "Additionally, 2,6′-DMC exhibited a significant inhibition of α-melanocyte-stimulating hormone (α-MSH)-induced melanin synthesis in B16F10 melanoma cells by downregulating tyrosinase, TRP-1, TRP-2, and MITF expression." (PMID 39996806, 2025). "Tyrosinase is a key enzyme responsible for melanin biosynthesis in the skin, making it a significant target for both cosmetic and anticancer therapies, particularly those targeting melanoma." (PMID 40332760, 2025). "Conversely, the accumulation of tyrosinase-mediated melanin may provide a protective effect against oxidative damage, thereby increasing melanoma cell survival under oxidative stress." (PMID 40332760, 2025). "It was revealed that TYR inhibitors could sensitize melanoma cells to the cytotoxic effects of cyclophosphamide and could enhance the activity of IL-2, reducing the effective cell proliferation inhibitory concentration from the original 10−3 M to 10−6 M." (PMID 40005101, 2025). "In addition, we applied this TYR-catalytic platform to activate anti-cancer prodrugs in situ through the CuAAC reaction, sensitizing drug-resistant melanoma to chemotherapeutics both in vitro and in vivo." (PMID 40651969, 2025). "However, the development of effective melanoma therapies based on tyrosinase inhibitors requires further intensive research." (PMID 41157098, 2025). "Using both B16 murine melanoma cells and a mouse hair follicle model, we assessed melanin production, TYR activity, and key melanogenic signaling molecules, providing mechanistic evidence for EUE as a candidate therapeutic for oxidative stress-induced hair depigmentation." (PMID 41496855, 2025). "Similarly, co-treatment with α-MSH and fisetin also led to a noticeable reduction in MITF and tyrosinase expression in melanoma cells." (PMID 41373883, 2025). "Hence, our study explored the effects of SPEF on MITF, TRP-1, TRP-2, and tyrosinase expressions in α-MSH-treated melanoma cells." (PMID 40003988, 2025). "Moreover, TYR has been considered one of the hypothetical therapeutic targets regarding melanoma due to its significant contribution to melanogenesis." (PMID 40005101, 2025). "T4FAT, another copper chelator, inhibited melanogenesis in melanoma cells, which was associated with a decrease in the TYR level but not the TYRP-1 level." (PMID 39970778, 2025). "In general, the human tyrosinase DNA melanoma vaccine was well tolerated by canine patients." (PMID 40284831, 2025). "For example, by using tyrosinase as a “needle” and dual-functionalized polysaccharides with tyrosine and triphenylphosphine as a “rope,” researchers constructed a melanin network within melanoma cells to target mitochondria and slow down tumor metabolism." (PMID 40599859, 2025). "Both TRP1 and TRP2 also suppress tyrosinase‐mediated cell death of melanocytes and melanoma cells." (PMID 40509563, 2025). "We investigated whether HE-chrysin can eliminate ROS production and inhibit TYR activity essential for melanin synthesis using in vitro B16F10 murine melanoma cells." (PMID 39882455, 2025). "Additionally, in α-MSH-induced melanoma cells, fisetin treatment led to about a 50-fold reduction in tyrosinase activity relative to the α-MSH group." (PMID 41373883, 2025).
melanoma (continued). "Since UV-induced oxidative stress may serve a central role in the dysregulation of melanogenesis in both melanocytes and melanoma cells, including the inhibition of tyrosinase activity, these compounds may help mitigate its effects." (PMID 40507810, 2025). "Therefore, research on tyrosinase inhibitors that can inhibit melanoma cell growth and proliferation is extremely important." (PMID 41157098, 2025). "Moreover, fisetin reduced the protein expression levels of MITF and tyrosinase in both human melanoma cells and α-MSH-stimulated melanoma cells." (PMID 41373883, 2025). "Therefore, we propose these five structures for further in silico studies on their applicability to the human tyrosinase enzyme, as well as experimental studies aimed at developing pharmaceutical formulations for melanoma treatment." (PMID 40143194, 2025). "This study showed that PE may target CREB1 and thus regulate the MITF/TYR/DCT axis to reduce melanoma cell viability and the production of melanin." (PMID 40369904, 2025). "T-6 (400 μmol/L) reduced melanin content in B16F10 melanoma cells by 71% and TYR activity by 79%." (PMID 38786597, 2024). "In this review article, we summarize the research progress of isoflavones in melanoma, including anti-melanoma roles and mechanisms of isoflavones via inhibition of tyrosinase activity, melanogenesis, melanoma cell growth, invasion of melanoma cells, and induction of apoptosis in melanoma cells." (PMID 38586368, 2024). "The increased tyrosinase activity may result in hyperpigmentation of the skin or even malignant melanoma." (PMID 39795088, 2024). "An example is a confirmation that protocatechuic acid may significantly suppress the melanin content and cellular tyrosinase activity in α-melanocyte stimulating hormone-stimulated mouse melanoma cells." (PMID 38257227, 2024). "Furthermore, reduced-sensitivity PCR has been proven to be more clinically relevant for detecting tyrosinase mRNA in melanoma patients." (PMID 39766118, 2024). "Additionally, all three banana peel extracts, along with their phenolic constitutes, significantly decreased TYR mRNA expression levels in the B16 mouse melanoma model." (PMID 39684912, 2024). "Thus, stimulation of melanin pigmentation in B16 melanoma and of tyrosinase activity in human melanoma cells and normal melanocytes was reported." (PMID 38927967, 2024). "However, in the G361 human melanoma cells, 95EtOH showed the most effective inhibitory effects against melanin production and intracellular tyrosinase activity." (PMID 39684912, 2024). "Lanostane-structured triterpenoids: hispindic acid A and B isolated from the fruiting bodies of Inonotus hispidus, whose structure was elucidated by extensive spectroscopic analysis (NMR and HRMS), were evaluated for their ability to activate melanogenesis and tyrosinase in B16 melanoma cells." (PMID 38474692, 2024). "The authors suggested that RT-PCR detection of tyrosinase mRNA is feasible and may serve as a stage-related marker for melanoma, warranting further research." (PMID 39766118, 2024). "Also, we will summarize it anti-melanoma mechanisms through inhibiting tyrosinase activity, reducing cell growth and invasiveness of melanoma, and inducing apoptosis of melanoma cells." (PMID 38586368, 2024). "Therefore, we are currently looking for effective tyrosinase inhibitors that can be used in melanoma therapy and food processing." (PMID 39409408, 2024). "Various synthetic and natural compounds may use to treat melanoma and skin diseases via target the TYR gene." (PMID 39541331, 2024). "Moreover, contrary to previous assumptions, amelanotic melanoma cells retain the ability to produce melanin, as demonstrated by the expression of tyrosinase and MITF." (PMID 39519055, 2024). "We took the view that bee pollen might be a potential source of TIPs with the capacity to inhibit the expression of TYR in B16F10 mouse melanoma cells through disruption of the melanogenesis signaling cascades." (PMID 39730661, 2024).
melanoma (continued). "grandiflorum significantly decreased the activity of tyrosinase in murine melanoma B-16 cells." (PMID 38929064, 2024). "Following UVB exposure, there is an upregulation of melanogenesis-related genes—such as microphthalmia-associated transcription factor, tyrosinase, tyrosinase-related proteins 1 and 2, Rab27A and myosin—in both B16F10 mouse melanoma cells and PIG1 human melanocyte cells." (PMID 39203946, 2024). "Tyrosinase (TYR) emerges as a key enzyme that exerts a regulatory influence on the synthesis of melanin, thereby assuming the role of a critical biomarker for the detection of melanoma." (PMID 38667195, 2024). "Moreover, the variations in TYR gene are associated with various genetic disorders affecting pigmentation, such as oculocutaneous albinism type 1 (OCA1) and melanoma." (PMID 39541331, 2024). "We also tested tyrosinase-dependent cytotoxicity using B16BL6 melanoma cells." (PMID 39337478, 2024). "As a result, pretreatment of the compound markedly reduced both intracellular and extracellular melanin levels by suppressing tyrosinase activity in α-MSH-induced B16F10 melanoma cells, demonstrating that its cellular tyrosinase inhibition was responsible for anti-melanogenic potential." (PMID 39457011, 2024). "Adult melanomas expressed tyrosinase (86.2%), MAGE-A3 (75.9%), NY-ESO-1 (48.3%), and TPTE (48.3%)." (PMID 38890171, 2024). "Therefore, a DOPA staining assay was conducted to assess the intracellular active form of tyrosinase in D. pannonicus-treated B16F1 melanoma cells." (PMID 39768251, 2024). "Additionally, the use of liposomal RNA vaccines targeting melanoma-associated antigens NY-ESO-1, MAGE-A3, tyrosinase, and TPTE, have shown efficacy in melanoma tumor regression as monotherapy or in combination." (PMID 39682188, 2024). "BioNTech developed a cancer mRNA vaccine, called FixVac (BNT 111), targeting simultaneously four melanoma TAAs, including New York esophageal squamous cell carcinoma 1 (NY-ESO-1), melanoma-associated antigen A3 (MAGE-A3), tyrosinase, and transmembrane phosphatase with tensin homology (TPTE)." (PMID 39081320, 2024). "A clinical trial showed that topical application of EGT could decrease the melanin index in UVA-irradiated human skin by inhibiting tyrosinase activity within melanoma cells." (PMID 38887673, 2024). "Our results illustrated that all banana peel extracts could inhibit melanin content as well as cellular tyrosinase activity in IBMX-induced B16 melanoma cells." (PMID 39684912, 2024). "Furthermore, sericin inhibits tyrosinase activity and promotes cell proliferation, which can be supportive and useful in melanoma treatment." (PMID 38732075, 2024). "MLANA and tyrosinase have been proposed as biomarkers for melanoma detection." (PMID 36614248, 2023). "TriMix, a mixture of monocyte-derived dendritic cells electroporated with mRNA encoding CD70, CD40 ligand, and constitutively active TLR4, as well as the tumor-associated antigens tyrosinase, gp100, MAGE-A3, or MAGE-C2 were administered together with ipilimumab in patients with advanced melanoma." (PMID 36830845, 2023). "Furthermore, SGMFAb inhibited serum-induced B16BL6 melanoma cell proliferation and attenuated α-MSH-induced melanin production and tyrosinase activity in B16BL6 melanoma cells." (PMID 38068567, 2023). "Vaccination with autologous dendritic cells loaded with mRNA encoding for melanoma-specific antigens (MAGE-A1, -A3, -C2, tyrosinase, MelanA/MART-1, or gp100), and an HLA class II-targeting sequence, has also been evaluated in 30 resected stage III/IV melanoma patients." (PMID 36992220, 2023). "In addition, the cytotoxicity of the optimal formulation of GAN against B16F10 melanoma cells and the antibacterial and TYR inhibitory activity were investigated compared with those of pure GA for cosmetic and pharmaceutical applications." (PMID 38139807, 2023).